CASKIN1 (CASK interacting protein 1)
Description:
May link the scaffolding protein CASK to downstream intracellular effectors.
Synonyms: KIAA1306; ANKS5A
Tractability: PROTAC: ubiquitination databases record sites on it; its protein half-life has been measured.
Gene: Protein-coding gene on chromosome 16 (2,177,180 to 2,196,605, reverse strand). Ensembl gene ENSG00000167971.
Subcellular location: Cytoplasm
Subcellular location (Human Protein Atlas): Nucleoplasm; Cytosol; Nuclear bodies
Gene Ontology:
Molecular function: identical protein binding; protein binding
Biological process: regulation of postsynaptic density assembly; signal transduction
Cellular component: cytoplasm; glutamatergic synapse; postsynapse
Genetic constraint (gnomAD): Loss-of-function variants: 42 observed, 88.5 expected, observed/expected ratio (o/e) 0.47, 90% interval 0.37 to 0.61. The synonymous counts are far from expectation, so gnomAD's model fits this gene poorly and the ratio says little. Missense variants: 2,072 observed, 1,781.1 expected, observed/expected ratio (o/e) 1.16, 90% interval 1.12 to 1.21. Synonymous variants: 1,142 observed, 826.66 expected, observed/expected ratio (o/e) 1.38, 90% interval 1.32 to 1.45.
Homologues: Orthologues: chimpanzee CASKIN1 (99% identical), macaque CASKIN1 (98% identical), pig CASKIN1 (92% identical), guinea pig CASKIN1 (91% identical), rat Caskin1 (90% identical), mouse Caskin1 (90% identical), tropical clawed frog caskin1 (66% identical), zebrafish caskin1 (57% identical), zebrafish si:dkeyp-9d4.3 (45% identical). Paralogues in human: CASKIN2 (38% identical).
Diseases named in the same sentence as CASKIN1 in open-access papers:
CASKIN1 is named in the same sentence as 16 diseases in open-access papers, as found by Europe PMC text mining. Sharing a sentence is not in itself a finding about the gene and the disease. The quoted sentences say what the papers report.
Anxiety (3 papers, 2018 to 2023). Intense feelings of nervousness, tension, or panic often arise in response to interpersonal stresses. "Recent data from Caskin1 knockout animals indicated only a mild role of Caskin1 in anxiety and pain perception." (PMID 31727973, 2019). "Based on numerous animal behavioural tests, they concluded that Caskin1 plays a slight role in anxiety, pain perception, gait control and spatial memory formation in the Barnes maze." (PMID 31727973, 2019). "In the light/dark transition test, distance traveled and time spent in the light chamber were significantly reduced in Caskin1-KO mice, suggesting elevated anxiety-like behavior." (PMID 30359304, 2018). "In the elevated plus maze test, Caskin1-KO mice exhibited a decrease in anxiety-like behavior, whereas in the light/dark transition and the open field tests, they exhibited both decreases and increases in anxiety-like behaviors." (PMID 30359304, 2018). "Additionally, anxiety-like behavior in the elevated plus maze test was attenuated in Caskin1-KO mice, as evidenced by their higher rate of entry into the open arms relative to wild-type mice." (PMID 30359304, 2018). "In tests of anxiety-like behavior, Caskin1-KO mice exhibited phenotypic discrepancies." (PMID 30359304, 2018). "To explain this observation, we speculated that Caskin1-KO mice were exhibiting panic-like escape behavior due to intense anxiety." (PMID 30359304, 2018). "Therefore, the increased pain transmission and anxiety-like behavior in Caskin1-KO mice might be mediated by 5-HT receptors." (PMID 30359304, 2018). "However, GluN2B Y1472F knockin-mice exhibit enhanced anxiety-like behavior in the elevated plus-maze test and impaired fear-related memory in auditory fear conditioning, both of which are contrary to the phenotypes in the Caskin1-KO mice." (PMID 30359304, 2018).
glioma (2 papers, 2021 to 2024). A benign or malignant brain and spinal cord tumor that arises from glial cells (astrocytes, oligodendrocytes, ependymal cells). "Briefly, LINC00294/miR-21-5p/CASKIN1 promoted glioma cell apoptosis and inhibited mitochondrial function via the cAMP pathway." (PMID 34777696, 2021). "Among the 14 candidate target genes, CASKIN1 was determined as the most downregulated gene in glioma, with the most significant difference." (PMID 34777696, 2021). "In conclusion, LINC00294 elevated the CASKIN1 expression by sponging miR-21-5p and activating the cAMP signaling pathway, thus inhibiting mitochondrial function and facilitating glioma cell apoptosis." (PMID 34777696, 2021). "Under hypoxic conditions and LINC00294 silencing, the apoptosis and mitochondrial function of glioma cells were detected after inhibiting miR-21-5p or overexpressing CASKIN1." (PMID 34777696, 2021). "To investigate the effect of LINC00294/miR-21-5p/CASKIN1 on glioma cell apoptosis, we transfected experimental cells with the miR-21-5p inhibitor or oe-CASKIN1 under hypoxia and LINC00294 silencing condition." (PMID 34777696, 2021). "To study the effect of LINC00294/miR-21-5p/CASKIN1 on the mitochondrial function of glioma cells under hypoxia, we measured the mtDNA level using RT-qPCR." (PMID 34777696, 2021). "Altogether, our findings revealed that LINC00294/miR-21-5p/CASKIN1 inhibited mitochondrial function in glioma cells under hypoxia via the cAMP pathway." (PMID 34777696, 2021). "To conclude, our findings elicited that silencing LINC00294 restored mitochondrial function and inhibited glioma cell apoptosis under hypoxia via the miR-21-5p/CASKIN1/cAMP axis." (PMID 34777696, 2021). "In the current study, CASKIN1 presented with the most downregulated expression in glioma among the candidate target genes." (PMID 34777696, 2021). "Currently, the physiological and pathological roles of CASKIN1 in glioma remain unidentified." (PMID 34777696, 2021). "The expressions of and relations among miR-21-5p, CASKIN1, and cAMP in glioma cells were analyzed." (PMID 34777696, 2021). "Inhibition of miR-21-5p or overexpression of CASKIN1 annulled the effects of LINC00294 silencing on mitochondrial function and glioma cell apoptosis under hypoxia." (PMID 34777696, 2021).
anxiety disorder (1 paper, 2023). A category of psychiatric disorders which are characterized by anxious feelings or fear often accompanied by physical symptoms associated with anxiety. "In contrast, the variant in CASKIN1 perfectly segregated with psychosis with the exception of two non-penetrant individuals (II-5 and I-3), although (I-3) had an anxiety disorder diagnosis and is an obligate carrier of any pathogenic variant in this pedigree in an autosomal dominant model." (PMID 36672919, 2023).
autism spectrum disorder (1 paper, 2022). A spectrum of developmental disorders that includes autism, and Asperger syndrome. "CASKIN1 alterations have in preclinical rodent models been seen to be responsible for the presentation of autism spectrum disorder (ASD) behavioral phenotypes." (PMID 35928685, 2022).
bipolar disorder (1 paper, 2023). A disorder of the brain that causes unusual shifts in mood, energy, activity levels and the ability to carry out day-to-day tasks. "Whole-exome sequencing of a large three-generation family with SCZ and bipolar disorder identified a single segregating novel, rare, non-synonymous variant in the gene CASKIN1." (PMID 36672919, 2023).
cognitive decline (1 paper, 2025). "Thus, the decrease in CASKIN1 may lead to a loss of synaptic integrity, potentially contributing to the cognitive decline observed in MDD by affecting the regulation of LTP in Excitatory.neurons_1 cells." (PMID 40243907, 2025).
depression (1 paper, 2020). "Although many of the top genes do not have direct disease association, several have been linked to depression-like behavior in animal studies such as PPP1R16A and CASKIN1." (PMID 31165141, 2020).
low grade glioma (1 paper, 2025). A grade I or grade II glioma arising from the central nervous system. "Additionally, correlation analysis in low-grade glioma (LGG) patients revealed a negative relationship between miR-21-5p and CASKIN1 expression, while Western blot results showed that miR-21-5p overexpression decreased CASKIN1 protein levels, and its inhibition increased CASKIN1 expression." (PMID 40243907, 2025).
prostate carcinoma (1 paper, 2018). A carcinoma that arises from epithelial cells of the prostate gland. "Five genes CGNL1, SUPV3L1, TATDN2, CASKIN1, and GOLGA7B are of unknown functions in either prostate cancer tumorigenesis or tumorigenesis in general." (PMID 30024105, 2018).
psychosis (1 paper, 2023). "Here, we report a large three-generation family segregating psychosis as an autosomal dominant trait with high penetrance, with a co-segregating previously unknown coding variant in CASKIN1." (PMID 36672919, 2023). "Taken together with CASKIN1’s close relationship with NRXN1, our data suggest that the identified variant is a strong candidate to be causing psychosis with high penetrance in this family." (PMID 36672919, 2023). "Our results suggest that CASKIN1 is an excellent gene candidate for psychosis development with high penetrance in this family." (PMID 36672919, 2023). "Definite proof of CASKIN1’s involvement in psychosis can only come from identification of additional families with similar pedigrees and mode of inheritance, yet our study strongly supports that CASKIN1 and the pre-synaptic signaling pathway involving it and NRXN1 warrants intensive study." (PMID 36672919, 2023). "This supports the validity of our results and implicates CASKIN1 in the development of psychosis." (PMID 36672919, 2023). "For these reasons, we are not making claims on CASKIN1 and the specific variant causing psychosis." (PMID 36672919, 2023). "Our observation that family members without psychosis who carry CASKIN1 D1204N have the lowest PRS for SCZ in the family at certain p-value thresholds is interesting, despite not reaching statistical significance due to the very small sample size." (PMID 36672919, 2023).
Stroke (1 paper, 2021). Sudden impairment of blood flow to a part of the brain due to occlusion or rupture of an artery to the brain. "Additionally, Caskin1 has been shown to be downregulated in an ischemia/reperfusion injury rat model system both at the mRNA and protein levels, indicating a potential role of Caskin1 in the pathomechanism of stroke." (PMID 33467043, 2021).
cancer (2 papers, 2021 to 2023). A tumor composed of atypical neoplastic, often pleomorphic cells that invade other tissues. "However, the involvement of CASKIN1 gene in cancer has rarely been studied." (PMID 33897701, 2021). "There are no reports on functional studies for the roles of CASKIN1/2 in cancer yet, and thus no reports about how the SAM domains affect their roles in cancer." (PMID 37296980, 2023).
tumor (2 papers, 2021). "CASKIN1 was overexpressed in tumor and its high expression was associated with poor OS, while high expression of EMR3 and GBP5 were associated with better survival." (PMID 33897701, 2021). "CASKIN1 expression was negatively correlated with the immune/stromal/Estimate scores and positively correlated with tumor purity." (PMID 33897701, 2021). "In comparison with the normal cells, the tumor cells showed notably reduced CASKIN1 and cAMP expressions." (PMID 34777696, 2021). "In comparison with those of the normal group, the expression patterns of CASKIN1 and cAMP in the tumor group were significantly reduced." (PMID 34777696, 2021). "Similar result was observed for pathological stage and tumor grade for CASKIN1 expression." (PMID 33897701, 2021). "Additionally, in our results, CASKIN1 was downregulated in the tumor samples of LGG and GBM collected by TCGA and GTEx." (PMID 34777696, 2021). "The results indicated that the expression of CASKIN1, EMR3, and GBP5 showed significant difference between the tumor and normal samples in both TCGA database and HPA." (PMID 33897701, 2021). "After identifying the prognostic value and expression level of CASKIN1, EMR3, and GBP5, we performed correlation analysis between CASKIN1, EMR3, and GBP5 expression levels and immune/stromal/Estimate scores, and tumor purity in HCC, respectively." (PMID 33897701, 2021). "Moreover, the expression levels of CASKIN1, EMR3, and GBP5 genes were significantly correlated with immune/stromal/Estimate scores or tumor purity and multiple immune cell infiltration." (PMID 33897701, 2021).
infection (1 paper, 2017). The state of being infected such as from the introduction of a foreign agent such as serum, vaccine, antigenic substance or organism. "The up-regulation of miR21a-5p after PHEV infection showed a sustained changes at 24, 48, and 60 h; however, Caskin1 mRNA and protein levels decreased 60 h post-infection compared to the 24 and 48 h time points." (PMID 28298907, 2017).
CASKIN1 also shares sentences with these, for which no sentence is quoted: autism (1 paper); psychiatric disease (1).